LEP (leptin)
Diseases named in the same sentence as LEP in open-access papers (continued):
Sharing a sentence is not in itself a finding about the gene and the disease.
cancer (continued). "Multivariable Cox regression was used to assess leptin and CRP levels (low, moderate, high) in relation to risk of cancer death." (PMID 26632325, 2016). "Normal breast tissue adjacent to cancerous tissue displayed increased leptin expression in 60% of the cases evaluated; in contrast, leptin was undetectable in the breasts of cancer-free women." (PMID 27338371, 2016). "An important role is played by leptin as a fundamental environmental regulator of CSCs in the cancer stem niche." (PMID 26556856, 2016). "On the other hand, higher cumulative mortality from cancer was noted in women with higher serum leptin (P = 0.006)." (PMID 26632325, 2016). "Leptin is an activator of cell proliferation and anti-apoptosis in several cell types and an inducer of cancer stem cells; its critical roles in tumorigenesis are based on its oncogenic, mitogenic, proinflammatory, and proangiogenic actions." (PMID 27653140, 2016). "Dual target therapies directed versus the decreasing response from leptin stimulation and increasing the response from adiponectin pathways have some potential for more efficacious cancer therapy." (PMID 27029038, 2016). "In recent years, studies revealed that levels of leptin and adiponectin were changed in MM patients and other cancer." (PMID 27863383, 2016). "Despite suggestive experimental findings, there is limited observational evidence documenting the importance of leptin‐inflammation interplay in cancer incidence or mortality." (PMID 26632325, 2016). "Leptin-induced activation of STAT3 regulates several genes involved in cancer, which include cyclin D1, cyclooxygenase (COX)-2, VEGF, human telomerase reverse transcriptase (hTERT), Survivin and leptin." (PMID 27472371, 2016). "We observed a protective effect of leptin against cancer death in women and higher cancer death with increased CRP in men." (PMID 26632325, 2016). "The impact of leptin on cell cycle gene and protein expression in different cancer cells is well established." (PMID 27480179, 2016). "If adiponectin has been shown to decrease growth and proliferation, increase apoptosis, decrease invasion and vessel density in murine cancer models, leptin has been shown to increase proliferation, migration, and invasion of cancer cells." (PMID 27029038, 2016). "Leptin at dose of 40 ng/mL (noted in plasma of overweigh human) had a stimulatory effect on both cancer cell lines proliferation." (PMID 27480179, 2016). "Epidemiological evidence showed that high levels of serum leptin (LEP) were associated with onset and progression of various cancers." (PMID 27768592, 2016). "The insulin/insulin-like growth factor (IGF) system and related pathways such as growth hormone, and leptin signaling have a key role in cancer development." (PMID 27942580, 2016). "Higher leptin level, in turn, contributed to cancer growth and development via stimulating inflammation, angiogenesis, proliferation and epithelial-mesenchymal transition." (PMID 27768592, 2016). "Overall, leptin regulation of JAK/STAT signaling has biological consequences during pathway hyperactivation in cancer and becomes further complicated by leptin-signaling interactions with other signaling pathways." (PMID 27472371, 2016). "STAT3 is part of a pathway that is critical for facilitating leptin actions on dietary intake, weight gain, and glucose metabolism; however, elevated levels have been correlated with poor prognosis among cancer patients." (PMID 27472371, 2016). "Thus, it is hypothesized that leptin dysregulation may contribute to cancer risk." (PMID 27636369, 2016). "Previous studies have documented that leptin is involved in the pathogenesis of many human cancer types by regulation of numerous signal transduction pathways." (PMID 27185268, 2016). "Adipokines including adiponectin and leptin which are secreted by adipose tissue have a role in cancer biology in obese people." (PMID 26199932, 2015).
cancer (continued). "To verify the effect of leptin on growth of cancer cells in our experimental conditions, we first investigated the effect of leptin on cell number using MTS assay." (PMID 25704884, 2015). "Several groups have developed short leptin fragments containing specific ObR interacting domains that demonstrated anti-neoplastic activity both in vitro and in vivo cancer models 31–35." (PMID 25721149, 2015). "Taken together, all these results provide evidence that autophagy activation plays a critical role in leptin-induced cancer cell growth via suppression of apoptosis." (PMID 25704884, 2015). "Based on previous reports, it is well accepted that autophagy plays an important role in the development of cancer and leptin induces tumor growth." (PMID 25704884, 2015). "Here, we review the role of adipose tissue from an endocrine perspective and outline the effect of adipokines on cancer metabolism, with particular focus on leptin." (PMID 26376613, 2015). "Leptin, a hormone mainly produced from adipose tissue, has been shown to induce proliferation of cancer cells." (PMID 25704884, 2015). "Evidence suggests that increased adiposity results in increased leptin secretion from adipose tissue, which has been shown to increased cancer cell proliferation." (PMID 26286584, 2015). "Several potential therapeutic approaches able to inhibit leptin activity, especially in obese cancer patients, have been proposed." (PMID 25721149, 2015). "A relationship between low fat mass and low plasma leptin levels has also been reported in cancer patients." (PMID 26508820, 2015). "Further, factors such as the type of cancer, BMI, and sex and age influence serum leptin concentration, as reported in adolescents, also need to be considered in study interpretation." (PMID 26508820, 2015). "Leptin exposure increased cancer cell migration/invasion through leptin-mediated activation of JAK/STAT3, PI3/AKT and RhoA/ROCK and promoted new lamellipodial, stress-fiber and focal adhesion formation." (PMID 26053184, 2015). "Increased leptin has been reported in subsets of cancer patients and demonstrated to stimulate proliferation of colon cancer cells, breast cancer cell migration, glioma migration and invasion, as well as the growth of cholangiocarcinoma cells in vitro." (PMID 25919692, 2015). "Leptin-induced tumor growth is mediated through suppression of apoptosis via down-regulating expression of apoptotic proteins, including Bax, in cancer cells, as well as stimulating cellular proliferation by activation of different types of kinase pathways." (PMID 25704884, 2015). "Although the leptin-stimulated enhancement of cell migration and invasion has been reported before in various cancers, the evidence was obtained from the in vitro experiments such as wound healing or Transwell assay." (PMID 25948792, 2015). "Compelling evidences have indicated that leptin stimulates growth of different types of cancer cells." (PMID 25704884, 2015). "A possible explanation for this interesting finding is that the cancer cells are triggered to secrete higher concentrations of leptin and other inflammatory cytokines." (PMID 26472027, 2015). "In vitro studies performed in BG-1, SKOV3 and OVCAR-3 cancer cells have shown that leptin stimulates cell growth and inhibits apoptosis." (PMID 26053184, 2015). "We chose an ascites sample collected from an overweight cancer patient with high leptin levels (above 10 ng/ml) and another from a healthy BMI patient with low leptin levels (under 5 ng/ml)." (PMID 26053184, 2015). "A more intriguing finding was that the isolated cancer cells began to adhere to a surface with low attachment properties upon exposure to ascites with high leptin levels." (PMID 26053184, 2015). "Recent studies from our lab and others have shown an important role of leptin in acquisition of mesenchymal characteristics, and survival of cancer stem cells (CSCs) in vitro and in vivo." (PMID 26359358, 2015).
cancer (continued). "We also found significantly higher circulating leptin levels among overweight cancer patients (25.7±3.1 ng/ml) compared with healthy BMI patients." (PMID 26053184, 2015). "To clarify the mechanisms for leptin-induced growth of cancer cells, we investigated the role of autophagy in modulation of apoptosis." (PMID 25704884, 2015). "At this concentration, leptin has been reported to significantly stimulate the growth of various cancer cells." (PMID 25948792, 2015). "More importantly, media enrichment with leptin or ascites both prompted faster Matrigel invasion of the cancer cells." (PMID 26053184, 2015). "An interesting finding was that medium aliquots obtained after exposing the fat tissues to cancer cells contained higher levels of leptin than unexposed CM." (PMID 26472027, 2015). "Taken together, these data indicate that leptin treatment stimulates various characteristics of autophagy in cancer cells." (PMID 25704884, 2015). "Aside from proliferation, leptin has also been shown to increase the migratory capacity of cancer cells." (PMID 25919692, 2015). "Emerging evidence has suggested that leptin, an adipokine related to energy homeostasis, plays a role in cancer growth and metastasis." (PMID 25948792, 2015). "More interestingly, we observed the attachment of isolated cancer cells in the wells supplemented with ascites containing high leptin levels, despite being grown on a low-adherence surface." (PMID 26053184, 2015). "Alterations in leptin expression contributes to the progression of various diseases, including cancers." (PMID 25893833, 2015). "Despite the fact that the leptin levels were significantly lower in the cancer patients compared with the benign-overweight group, the levels were still significantly higher than the benign or malignant healthy BMI counterparts." (PMID 26053184, 2015). "In fact, we have recently discovered that high leptin levels stimulate the secretion of other cytokines (e.g., IL-6) both from cancer cells and from other cell types present in the ascites (e.g., macrophages; manuscript in preparation)." (PMID 26053184, 2015). "Increased energy balance, which culminates in increased adiposity, changes the levels of hormones such as insulin, adiponectin, leptin and IGF-1, which is also associated with cancer including ovarian." (PMID 25895126, 2015). "Many adipokines (such as leptin) and other cytokines secreted by adipose tissue (such as IGF-1), have been linked to cancer pathogenesis." (PMID 24926474, 2014). "Among these, the adipokine leptin is the most intensively studied in both metabolism in general and in cancer due to the fact that leptin levels increase in proportion of fat mass." (PMID 25505738, 2014). "Several studies have shown that leptin can act as a growth factor promoting proliferation of transformed cells and stimulating angiogenesis in cancers like endometrium and breast." (PMID 24867470, 2014). "Leptin appears to be a positive factor for tumor development and aggressiveness, while adiponectin protects against cancers." (PMID 25291184, 2014). "There is increasing evidence that adiponectin and leptin, secreted by peritumoral adipose tissue in several cancers including breast, are important." (PMID 25291184, 2014). "Our results also support the findings in various cancer cell lines indicating that leptin and adiponectin exert opposing effect in UCC carcinogenesis." (PMID 25115836, 2014). "Ghrelin and leptin are promising biomarkers to diagnose cachexia and to predict survival in cancer patients." (PMID 25400234, 2014). "Our results support the inclusion of ghrelin and leptin among those factors able to influence survival in cancer patients." (PMID 25400234, 2014). "In the context of cancer, insulin signaling and thus the role of leptin in the regulation of pancreatic β-cell functions are of importance." (PMID 24587106, 2014).
cancer (continued). "Significantly higher levels of both leptin and ObR expression have been found in cancer tissue relative to non-cancer epithelium." (PMID 25866478, 2014). "Leptin, primarily produced by adipocytes in proportion to body fat, has been postulated to play a major role in the pathophysiology of cancer cachexia." (PMID 25400234, 2014). "Our pharmacological and genetic studies demonstrate that leptin is the key peripheral effector in the HSA axis mediating the anti-cancer effect of EE." (PMID 24587106, 2014). "The importance of resistin in cancer cachexia appears to be different from this, which was proposed for leptin in our previous study." (PMID 25049439, 2014). "Accordingly with cancer stages, patients in stage IV showed the highest ghrelin levels (683.5 ± 73.4 ng/ml), the lowest leptin (19.67 ± 11.5 ng/ml) and obestatin values (9.2 ± 4.1 ng/ml) with respect to stage III." (PMID 25400234, 2014). "One of the adipokines that is elevated in obesity is leptin, which has been shown to promote the growth of several types of cancer." (PMID 24926474, 2014). "Leptin and OBRs have been reported to be overexpressed in numerous types of cancer and cancer cell lines." (PMID 23425972, 2013). "Serum leptin concentrations were significantly lower in the group of cancer survivors compared to controls; however, in those overweight from examined group we found leptin levels higher than those in nonoverweight." (PMID 24319457, 2013). "In invasive human cytotrophoblast, whose invasive potential closely resembles cancer cells, leptin induced α5 and α6 integrins and MMP9 activity." (PMID 24202338, 2013). "Numerous epidemiological studies have examined associations of genetic variations in LEP (G2548A, -2548 nucleotide upstream of the ATG start site) and LEPR (Q223R, nonsynonymous SNP in exon 6) with cancer susceptibility; however, the findings are inconsistent." (PMID 24146750, 2013). "Adiponectin and leptin have been subject to much study in cancer development as they are the most abundant adipokines." (PMID 24073332, 2013). "Remarkably, it was recently affirmed, the potential contribution of stroma fibroblasts to the paracrine effects of leptin on cancer cells." (PMID 24202338, 2013). "In the present study, leptin concentrations in the control group were statistically higher than in cancer survivors, but predominance of girls in the control group can be responsible for this." (PMID 24319457, 2013). "Higher leptin levels can be a factor for fostering cancer development and progression since it is now known to be mitogenic, proinflammatory, antiapoptotic, and proangiogenic." (PMID 24073332, 2013). "Cancer-transformed and “educated” fibroblasts played an essential role contributing to the progression of cancer via leptin signaling crosstalk." (PMID 24202338, 2013). "Leptin levels are significantly lower in patients with inflammatory states such as cancer despite correction for body fat." (PMID 22518191, 2012). "It has been reported that the blood concentration of leptin, as well as the amount of leptin in the tissue, is related to the progression of several cancers besides the prostate." (PMID 22654635, 2012). "It appears that leptin-mediated proliferation of these cancers occurs through the activation of the JAK-STAT, PI3K, and MAPK pathways, whereas apoptosis avoidance is promoted by leptin via the JAK-STAT and PI3K pathways." (PMID 22263109, 2012). "In GBM and other cancer cells, leptin promotes cancer by stimulating cellular pathways that are advantageous for proliferation, angiogenesis, and evasion of death." (PMID 22263109, 2012). "The pro-tumorigenic effect of leptin appears to be mediated in part by its stimulation of cancer cell proliferation via ERK, JNK, and STAT3 pathways." (PMID 23369448, 2012). "This beta-adrenergic stimulation suppresses leptin secretion resulting in cancer inhibition and remission." (PMID 22263109, 2012).
cancer (continued). "Other cancer-permissive functional activities of leptin include promotion of angiogenesis, apoptosis, and cellular migration." (PMID 22853725, 2012). "Adiponectin, C-Reactive Protein, and Leptin are key components of the chronic inflammatory environment that have been associated with elevated SUA levels and cancer." (PMID 23369448, 2012). "We found significantly lowered leptin concentrations (gender dependent) in the carcinoma group compared to BD." (PMID 23173608, 2012). "The amount of leptin hormone in cancer patients was higher than that in normal individuals, significantly (P < 0.05)." (PMID 22007338, 2011). "Exposure of cancer cells to hypoxic conditions and/or elevated concentrations of growth factors, such as insulin, can activate production of endogenous leptin, raising intratumoral levels of this hormone." (PMID 21771332, 2011). "The Important molecular pathways, such as JAK/STAT3, PI3K/AKT, ERK/MAPK, in many cancer cells can be activated by leptin/leptin receptors." (PMID 22007338, 2011). "The downregulation of leptin production in cachectic cancer patients is in agreement with a fall of adiposity in cancer cachexia." (PMID 21245862, 2011). "Leptin-mediated activation of mTOR, a pathway deregulated in many cancers, was involved in the regulation of IL-1 system." (PMID 21139583, 2011). "In contrast, serum leptin levels were lower (by 53%, P=0.035) in cachectic patients compared with weight-stable cancer patients." (PMID 21245862, 2011). "Multiple studies demonstrated that leptin is able to stimulate survival, proliferation, migration and invasiveness of several cancer cell types." (PMID 21771332, 2011). "In marked contrast to the results of ZAG, SAT leptin mRNA, which increases with fat mass accretion, is decreased in cachectic cancer patients." (PMID 21245862, 2011). "The connection of cancer with the system of leptin and its receptors has to be considered as a dynamic and changeable system in relation to the external and internal environment." (PMID 22363883, 2011). "Cumulatively, present and previous data suggest the involvement of tissue hypoxia in the stimulation of leptin and ObR expression in human cancers." (PMID 20569445, 2010). "The possible role of the inflammatory cytokines in the development and spread of cancer cells led us to examine the involvement of leptin in the production of IL-1a, IL-1b, IL-6 and TGF-β1 by human HCC cells." (PMID 20723213, 2010). "Upon leptin activation, the OB-R isoforms can utilize a number of diverse signaling pathways relevant to cancer growth." (PMID 19531256, 2009). "Considering the fundamental role of leptin and Ob-R in cancer development and progression, we sought to examine the expression pattern of leptin and Ob-R in large cohort of Middle Eastern EOC using TMA immunohistochemical analysis." (PMID 19765303, 2009). "White adipose tissue is the primary source of leptin in benign tissue, but leptin is also expressed and secreted by cancer cells." (PMID 19531256, 2009). "In summary, all these data clearly support a direct functional role of leptin in processes related to cancer initiation and/or progression by promoting the migration and proliferation of carcinoma cells, thus resulting in metastatic development." (PMID 20030801, 2009). "Leptin mediated signaling pathways play an important role in cancer cell proliferation, invasion and metastasis." (PMID 19765303, 2009). "Other studies explain the leptin stimulating effect on migration and invasion of various carcinoma cells through the increased expression of various matrix metalloproteinase or integrins via an activation of the nuclear factor κB (NFκB) pathway." (PMID 20030801, 2009). "Specifically, leptin can promote cancer cell growth and transformation in vitro and in vivo, and increase cell survival in the presence of anti-cancer drugs." (PMID 18945363, 2008).